INS (insulin)
Diseases named in the same sentence as INS in open-access papers (continued):
Sharing a sentence is not in itself a finding about the gene and the disease.
diabetes (continued). "Administration of hybrid insulin peptide-coupled PLG NPs was found to prevent diabetes by impairing the ability of CD4+ T cells to produce proinflammatory cytokines through induction of anergy, leading to an increase in the ratio of Foxp3+ regulatory T cells to IFN-γ+ effector T cells." (PMID 35336018, 2022). "With further improvements of conditions and administration methods, this could represent a feasible approach to be translated in the clinical setting in order to achieve positive results on insulin production and diabetes reversal." (PMID 35186929, 2022). "Diabetes mellitus is a clinical condition that causes a high amount of glucose in the blood with a simultaneous lack of insulin or insulin resistance." (PMID 35808386, 2022). "The objective of this study was to investigate whether serpentine could modulate the role of insulin in regulating blood glucose through insulin receptors in cells and in animal models of diabetes." (PMID 36678512, 2022). "However, a few studies reported no change in pY-IRS-1 in the muscle of Ob/Ob mice and obese rats with diabetes, even after insulin activation." (PMID 36547071, 2022). "This relationship was also used as an example, including the metabolite “Leucine” (D007930), the researcher’s known keyword “Diabetes Mellitus, Type 2” (D003924), and the answer keywords “Insulin resistance” (D007333) and “Mechanistic Target of rapamycin complex 1” (D000076222)." (PMID 35208208, 2022). "Moreover, a meta-analysis of 11 individual studies showed that RSV consumption significantly reduced fasting glucose, insulin, glycated hemoglobin, and insulin resistance levels in the subgroup of diabetes patients." (PMID 35056739, 2022). "Also designated mutant INS-gene induced diabetes of the young (MIDY), this syndrome defines molecular determinants of foldability in the endoplasmic reticulum (ER) of β-cells." (PMID 35299972, 2022). "Although these two forms of diabetes are fundamentally very different, β-cell failure and death play a key role in the pathogenesis of both diseases, leading to hyperglycemia resulting from a reduced capacity to produce insulin." (PMID 36142518, 2022). "Thus, RV IgG is accompanied by the appearance of autoantibodies and, as a result, accelerated β-cell damage and decreased insulin production, as seen by lower C-peptide in the IgG+ diabetes group." (PMID 35733062, 2022). "The main findings for the diabetes group analysis showed that some differences were due to HbA1c grouping (managed or unmanaged); BMI percentile and classification (e.g., obese or overweight), and diabetes management type (insulin injection or pump)." (PMID 36508408, 2022). "For type 1 diabetes mellitus, the patient will require insulin, the dosage of which may also need to be adjusted during each trimester of the pregnancy." (PMID 40041212, 2022). "For instance, Hispanic patients with diabetes who use apps are more likely to use certain functionalities such as medication and blood glucose diaries and less likely to use diaries developed for insulin and hemoglobin A1c." (PMID 35119368, 2022). "β-cells within pancreatic islets of Langerhans secrete insulin and are compromised in diabetes." (PMID 36099294, 2022). "Therefore, the disruption of insulin signaling is thought to be a common feature of both AD and diabetes." (PMID 35701718, 2022). "Although this is not a physiologically accurate progression of T2D, it illustrates a willingness to improve health status and an understanding that insulin injections may be required if their diabetes is poorly controlled." (PMID 36508418, 2022). "Therefore, we studied the effect of combination therapy with GABA and MgSO4 to improve insulin sensitivity in diabetes induced by streptozotocin as well as high-fat diet in a diabetic rat model." (PMID 35211170, 2022).
diabetes (continued). "Metformin was the most frequently used glucose-lowering medication (used by 1135 patients or 47.4% of the patients with diabetes) followed by insulin (used by 657 patients or 27.4% of the patients with diabetes) and sulfonylureas (used by 480 patients or 20.0% of the patients with diabetes)." (PMID 35717169, 2022). "Diabetes is a disorder in which not enough insulin is produced or cells are resistant to insulin, which causes blood sugar levels to be abnormally high or low." (PMID 35054301, 2022). "Ethnic differences regarding insulin sensitivity and secretion have been observed in populations that have not yet developed diabetes, thus different mechanisms are likely to contribute to diabetes development in diverse ethnic populations." (PMID 36247141, 2022). "Diabetes produces an inflammatory status in the body affecting the regulation of glucose and insulin sensitivity that, under COVID-19 infection, might promote the cytokines systemic inflammation response." (PMID 36498037, 2022). "Therefore, it is unlikely that misclassification of IR among insulin-treated women with diabetes would change the results." (PMID 36342714, 2022). "Consequently, in the immediate post-transplant setting, insulin therapy or prescription of a medication for diabetes is generally required to manage postoperative hyperglycemia, especially given the requirement for high-dose immunosuppressants in this setting." (PMID 35449717, 2022). "Diabetes is an illness in which the body produces insufficient insulin." (PMID 36611472, 2022). "Moreover, Lp299v supplement modulated antioxidative defense and ER stress responses in β-cells, potentially offering a new therapeutic direction to thwart diabetes progression and preserve insulin secretion." (PMID 36261888, 2022). "Furthermore, downregulation of miR-200a decreased insulin sensitivity, whereas upregulation of miR-200a in diabetic rats improved diabetes." (PMID 36299884, 2022). "However, we assessed the CCI and DCSI scores and insulin and oral antidiabetic use to evaluate the severity of diabetes; we used the clinical diagnosis to divide participants into compensated and decompensated liver cirrhosis." (PMID 36618937, 2022). "Secondly, with reference to the CONCEPTT study, diabetes management evolved over the years of the study with the increasingly frequent use of an insulin pump, continuous glucose monitoring systems, and the use of new insulin analogs." (PMID 34694409, 2022). "On the other hand, dyslipidemia-induced fat deposition could aggravate the dysfunction of pancreatic beta cells and inhibit insulin-stimulated glucose uptake and glycogen synthesis in diabetes." (PMID 35754684, 2022). "It was reported for the first time that P. atlantica leaf methanol extract and its sub-extracts did not have a significant effect against the PTP1B enzyme, which has an essential role in diabetes and obesity and is a negative regulator of leptin and insulin signaling pathways." (PMID 35281888, 2022). "Diabetes mellitus is a multifactorial metabolic disorder whose main cause is an absolute or relative lack of insulin, or the peripheral tissues are not sensitive to insulin." (PMID 35656112, 2022). "Hence, all people with diabetes who use insulin should have access to their life-sustaining medication." (PMID 35436214, 2022). "Interestingly, some other studies have reported insulin levels to be lower in the HFD/low dose STZ diabetes induction model despite the spike in blood glucose levels." (PMID 35739183, 2022). "According to that literature review, the majority of phytochemicals with antidiabetic bioactivity in the plant root system are engaged in the treatment of diabetes by lowering hyperglycemia and hyperlipidemia, inhibiting glucosidase, and regulating insulin secretion." (PMID 35899227, 2022).
diabetes (continued). "Diabetes has become a serious concern to people's health because it includes the pancreas' failure to generate enough insulin for blood sugar control or the body cells' difficulty to utilise the insulin that is produced." (PMID 35426251, 2022). "The left ventricular internal diameter end diastole increased with diabetes, and insulin treatment did not reverse the diabetes-associated change." (PMID 35574440, 2022). "Prolactin can protect β-cells from ER stress through the JAK2/STAT5 pathway, transcription factors such as GLIS3 can enhance INS gene expression, rapamycin can improve diabetes and further down-regulate β-cell apoptosis, and induced pluripotent stem cells can promote β-cell regeneration." (PMID 36686471, 2022). "Thus, drugs enhance insulin production and/or increase insulin sensitivity are being developed to treat diabetes." (PMID 35619170, 2022). "Therefore, our simulated diabetes model was defined as an environment of 20 mmol/L glucose + 100 nmol/L insulin for 9 days, while the control groups consisted of cells treated with 5.5 mmol/L glucose for the same period." (PMID 35835939, 2022). "Type-2 diabetes mellitus leads to inefficient insulin production." (PMID 35197753, 2022). "DNA methylation could be involved in glucose metabolism, insulin resistance, and other conditions, leading to the pathogenesis of diabetes that continues to be an area of active research." (PMID 36014850, 2022). "Second, some participants may have had difficulty accurately recalling past events, such as needle stick injuries, duration of diabetes diagnosis, and duration of insulin use, so we cannot exclude the possibility of recall bias." (PMID 36568796, 2022). "Furthermore, a recent study reported that mTOR was differentially involved in tubular autophagy activity via the insulin/mTOR pathway in the presence of nephropathy, depending on the type of diabetes." (PMID 36299884, 2022). "These rats were able to attenuate the symptoms of diabetes by increasing insulin production." (PMID 36140793, 2022). "We also determined whether patients had preexisting or new-onset diabetes to help facilitate glucometer and insulin teaching for patients new to these therapies." (PMID 35601713, 2022). "Linkage studies and genome-wide association studies have demonstrated that most risk variants for type 2 diabetes mellitus act through impaired insulin secretion, implying that β-cell dysfunction rather than insulin action is genetically determined." (PMID 35453469, 2022). "The profibrotic properties of insulin may contribute to the understanding of why diabetics have worse clinical outcomes with insulin use." (PMID 35574440, 2022). "In addition, G319S carriers reportedly showed a decrease in insulin secretion before diabetes appeared." (PMID 35299962, 2022). "However, after further adjustment of the use of medication (including diabetes pills or insulin), the protective effect of DPA disappeared." (PMID 36079863, 2022). "A recent study has reviewed that Aβ could affect insulin sensitivity, reduce glucose-dependent insulin secretion and contribute to the onset of diabetes." (PMID 35941691, 2022). "Diabetes-associated cognitive decline (DACD), one of the complications of type 2 diabetes (T2DM), correlates significantly with the disorder in glycolipid metabolism, insulin/leptin resistance, and accumulation of β-amyloid (Aβ)." (PMID 35721013, 2022). "Diabetes mellitus is a metabolic illness defined by unusually high blood sugar levels caused by a lack of the hormone insulin, impaired tissue sensitivity to insulin, or both." (PMID 36188660, 2022). "This study aimed to determine the risk of clinically significant biochemical hypoglycemia (CSBH) by HbA1c, gestational weight gain, C-peptide, mean capillary plasma glucose, and total insulin dose in pregnant women with type 1 diabetes mellitus in each trimester of pregnancy." (PMID 35207323, 2022).
diabetes (continued). "Individuals who are overweight, especially around the stomach, are more insulin safe and may battle to keep up with great diabetes control." (PMID 35268815, 2022). "Diabetes is one of the major metabolic diseases related to obesity, and current drugs result in the transient glucose‐controlling effect due to their function through enhancement of glucose uptake into insulin sensitive tissues such as liver and pancreas." (PMID 35384342, 2022). "In addition, another recycling endosome marker, Rab11B, showed a similar distribution within the islet; it also did not colocalize with glucagon but colocalized with insulin; this pattern remained unchanged in diabetes." (PMID 34923907, 2022). "However, it remains possible that spermidine negatively affected the insulin granule pool in NOD mice before diabetes manifestation." (PMID 35296698, 2022). "There is a direct link between diabetes and pancreatic damage (impaired insulin secretion)." (PMID 35725834, 2022). "Moreover, evidence supporting the efficacy of oral antidiabetic drugs to reduce hyperglycemia in response to PN is very weak and most patients with diabetes require supplemental insulin when glucose is infused." (PMID 36992742, 2022). "Along with the progression of diabetes induced by insulin deficiency, vascular fibrosis and stiffness and activated RAAS drive up blood pressure, which reflects the indirect effect of insulin on SBP via diabetes." (PMID 36589843, 2022). "However, modern diabetes therapy based on insulin injections and cadaveric islets transplantation has many disadvantages." (PMID 35740935, 2022). "Diabetes mellitus, more simply called diabetes, is a chronic condition that occurs when blood glucose levels rise because the body cannot produce any or enough of the hormone insulin or cannot effectively use the insulin it produces [...]." (PMID 36079100, 2022). "Taken together, this study suggests that Limosilactobacillus fermentum MG4295 could be usable as a functional food and nutraceutical to prevent diabetes by modulating the insulin and gluconeogenesis signaling pathways." (PMID 35053962, 2022). "Thus, we characterize patients of cluster C6 as diabetics mostly consuming insulin, whilst patients of C3 as diabetics consuming biguanides." (PMID 36064616, 2022). "For instance, in addition to hospitalizations and physician visits, diagnoses of diabetes were also identifiable through prescriptions of insulin, metformin and other oral antihyperglycemic, allowing the detection of current diabetes cases within a shorter observation period." (PMID 34991473, 2022). "Before admission, 72% of the treated diabetes group received a dipeptidyl peptidase-4 inhibitor, 40% metformin, 8% pioglitazone, 44% sodium glucose transporter 2 inhibitors, 4% glucagon-like peptide 1 analog, and 12% insulin." (PMID 35079646, 2022). "Insufficient insulin in the bloodstream leads to type 1 or type 2 diabetes mellitus." (PMID 35795141, 2022). "A negative association between pancreatic fat and insulin secretion has been found in subjects with a high genetic risk for diabetes." (PMID 35733870, 2022). "Four major type 1 diabetes (T1D)-associated autoantibodies to insulin (IAA), glutamate decarboxylase 65 (GADA), islet antigen-2 (IA-2A), and zinc transporter 8 (ZnT8A) remain primary biomarkers for predicting future diabetes and are distinctive clinical features of islet autoimmunity." (PMID 36181724, 2022). "One of the well-established agents in diabetes treatment is metformin, which lowers blood glucose levels through a decrease in hepatic gluconeogenesis, intestinal reabsorption of insulin and the improvement of sensitivity to insulin." (PMID 36012897, 2022). "Insulin signalling leads to type 2 diabetes mellitus and obesity (the process of dietary fat absorption is changed) is common.Obesity modifies peripheral tissues in response to insulin, where white adipose tissue, liver, and muscle playing major roles in the development of insulin resistance." (PMID 35815199, 2022).
diabetes (continued). "We also controlled for insulin analog use, severe chronic complications of diabetes, and obesity." (PMID 35111222, 2022). "Similarly, AdipoR1 mRNA was also increased in the skeletal muscle of T2D db/db obese and Lepr–/–mice, in which the overexpression of AdipoR1 prevented diabetes by improving insulin sensitivity." (PMID 35055468, 2022). "Hence, the PPARG agonist is important for increasing glucose tolerance by boosting insulin sensitivity and the functionality of beta cells in diabetics." (PMID 35207564, 2022). "Higher PRL levels are associated with higher insulin sensitivity and a lower incidence of type 2 diabetes mellitus, which led to a re-evaluation of current thresholds for normal PRL levels and hyperprolactinemia." (PMID 36157442, 2022). "Such innovative methods are needed at a time when the COVID-19 pandemic highly impacted diabetes care worldwide with a drop in access to insulin, decreased admission to hospital for patients in need of professional care, and many outpatient clinics shutting down." (PMID 36078271, 2022). "The lack or insufficiency of pancreatic endocrine function resulting from loss of β-cell mass, disrupted insulin secretion and/or impaired insulin action in target tissues leads to a permanent high level of blood glucose (hyperglycaemia) and diabetes mellitus (DM)." (PMID 36557308, 2022). "Insulin opposition is supported by instinctive fat, which raises the danger of diabetes." (PMID 35268815, 2022). "Similarly, the severity of diabetes in guinea pigs and the Chinese hamster is a function of reduced insulin synthesis and is directly related to the number of surviving functional β-cells." (PMID 35529919, 2022). "Compared with patients without a CVD history, those with a CVD history had an older age, a longer duration of diabetes, a lower prevalence of type 1 diabetes, and a higher prevalence of male sex, insulin use, anti-hypertensive medication, and anti-hyperlipidemic medication." (PMID 34462827, 2022). "Additionally, magnesium supplementation is known to improve insulin sensitivity and metabolic control in patients with diabetes." (PMID 35683428, 2022). "INS-1E cells and cells derived from human pancreatic islets have been shown to be highly susceptible to LATS2 deficiency, resulting in improved viability, increased cell mass, and restoration of insulin secretion, which combine to reduce the development of diabetes." (PMID 35054822, 2022). "Diabetes develops in these patients likely due to pancreatic β cell dysfunction, decreased insulin secretion, and increased insulin resistance in other tissues, which may depend on the timing and the dose of GCS used." (PMID 35055050, 2022). "According to our results, nurses were the primary provider of sharps disposal information, which may result from the fact that education on insulin injection in China is mainly performed by nurses and diabetes educators." (PMID 36568796, 2022). "Some reported taking multiple non-insulin diabetes medications." (PMID 36221145, 2022). "However, to our knowledge, there is little information on the clinical features and sequelae of people with diabetes that require insulin when admitted with SARS-CoV-2 infection." (PMID 35256883, 2022). "However, with the decrease in insulin sensitivity, this relationship becomes positive; for example, irisin levels have been reported to be higher in individuals with diabetes mellitus." (PMID 35040046, 2022). "In view of the abnormal fetal growth parameters in this non‐obese mother with insulin‐treated diabetes who has a strong maternal family history of young uncomplicated diabetes, she was referred to an endocrinologist and the alternative diagnosis of GCK‐MODY was considered." (PMID 36483860, 2022).